FLVCR1 (FLVCR choline and heme transporter 1)
Description:
Uniporter that mediates the transport of extracellular choline and ethanolamine into cells, thereby playing a key role in phospholipid biosynthesis. Choline and ethanolamine are the precursors of phosphatidylcholine and phosphatidylethanolamine, respectively, the two most abundant phospholipids. Transport is not coupled with proton transport and is exclusively driven by the choline (or ethanolamine) gradient across the plasma membrane. Also acts as a heme b transporter that mediates heme efflux from the cytoplasm to the extracellular compartment. [Isoform 1]: Uniporter that mediates the transport of extracellular choline and ethanolamine into cells. Choline and ethanolamine are the precursors of phosphatidylcholine and phosphatidylethanolamine, respectively, the two most abundant phospholipids. Transport is not coupled with proton transport and is exclusively driven by the choline (or ethanolamine) gradient across the plasma membrane. Also acts as a heme b transporter that mediates heme efflux from the cytoplasm to the extracellular compartment. Heme export depends on the presence of HPX and is required to maintain intracellular free heme balance, protecting cells from heme toxicity. Heme export provides protection from heme or ferrous iron toxicities in liver, brain, sensory neurons and during erythropoiesis, a process in which heme synthesis intensifies. Possibly export coproporphyrin and protoporphyrin IX, which are both intermediate products in the heme biosynthetic pathway. Does not export bilirubin. The molecular mechanism of heme transport, whether electrogenic, electroneutral or coupled to other ions, remains to be elucidated. [Isoform 2]: Heme b transporter that promotes heme efflux from the mitochondrion to the cytoplasm. Essential for erythroid differentiation. [Isoform 1]: (Microbial infection) Confers susceptibility to feline leukemia virus subgroup C (FeLV-C) infection in vitro.
Synonyms: SLC49A1; FLVCR; MFSD7B; PCA; AXPC1; NEDMISH; PCARP; RETSNS
Tractability: Small molecule: a structure with a bound ligand is known. Antibody: UniProt places it where antibodies can reach, with high confidence; its Gene Ontology location is reachable by antibodies, with high confidence; UniProt predicts a signal peptide or a membrane-spanning region. PROTAC: ubiquitination databases record sites on it.
Gene: Protein-coding gene on chromosome 1 (212,858,237 to 212,899,363, forward strand). Ensembl gene ENSG00000162769.
Subcellular location: Cell membrane (Isoform 1); Mitochondrion membrane (Isoform 2)
Subcellular location (Human Protein Atlas): Cell Junctions
Pathways (Reactome):
Metabolism: Heme biosynthesis
Transport of small molecules: Iron uptake and transport
Gene Ontology:
Molecular function: choline transmembrane transporter activity; ethanolamine transmembrane transporter activity; heme transmembrane transporter activity; protein binding; heme binding; transmembrane transporter activity
Biological process: choline transport; erythrocyte differentiation; heme export; heme transport; mitochondrial transport; phospholipid biosynthetic process; heme biosynthetic process; intracellular iron ion homeostasis; ethanolamine transport; transmembrane transport
Cellular component: mitochondrial membrane; mitochondrion; plasma membrane; membrane; mitochondrial inner membrane
Genetic constraint (gnomAD): Loss-of-function variants: 25 observed, 34.48 expected, observed/expected ratio (o/e) 0.73, 90% interval 0.53 to 1.01. The upper end of that interval is the gene's LOEUF score, 1.01, which puts it in group 4 of 6, group 1 being the genes least tolerant of losing a copy. Missense variants: 555 observed, 548.13 expected, observed/expected ratio (o/e) 1.01, 90% interval 0.94 to 1.09. Synonymous variants: 255 observed, 239.78 expected, observed/expected ratio (o/e) 1.06, 90% interval 0.96 to 1.18.
Gene-disease validity (ClinGen):
ClinGen rates the evidence that FLVCR1 causes each of these diseases.
FLVCR1-related retinopathy with or without ataxia (autosomal recessive): Definitive. A disorder characterized by retinopathy with ataxia in most patients, caused by biallelic variants in the FLVCR1 gene.
Homologues: Orthologues: chimpanzee FLVCR1 (99% identical), macaque FLVCR1 (98% identical), rabbit FLVCR1 (88% identical), dog FLVCR1 (86% identical), pig FLVCR1 (84% identical), guinea pig FLVCR1 (83% identical), rat Flvcr1 (81% identical), mouse Flvcr1 (79% identical), tropical clawed frog flvcr1 (65% identical), zebrafish flvcr1 (61% identical), Drosophila melanogaster HisT (41% identical), Caenorhabditis elegans C09D4.1 (39% identical). Paralogues in human: FLVCR2 (50% identical), SLC49A3 (23% identical), SLC49A4 (22% identical), CFAP276 (7% identical).